TMPRSS2 (transmembrane serine protease 2)
Diseases named in the same sentence as TMPRSS2 in open-access papers (continued):
Sharing a sentence is not in itself a finding about the gene and the disease.
prostate carcinoma (continued). "Transmembrane protease serine 2 (TMPRSS2), an androgen-induced protease in prostate cancer, has been implicated in influenza and coronavirus entry into the host cell, triggering host immune response." (PMID 34341347, 2021). "In prostate cancer cells, androgenic hormones up-regulate the TMPRSS2 gene which probably is mediated by the androgen receptor." (PMID 34527703, 2021). "Judging from the protease selectivity data and potency of MM3122 and other new compounds, these are predicted to also show corresponding anticancer activity, in particular for HGF-driven prostate cancer for which TMPRSS2 is known to play a key role." (PMID 34635581, 2021). "In this trial, we repurpose the FDA approved LHRH antagonist degarelix, commonly used for prostate cancer, to suppress TMPRSS2, a host cell surface protease required for SARS-CoV-2 cell entry." (PMID 34225789, 2021). "Tian and colleagues used a newly established prostate cancer cell line (PC3c), derived from PC-3, to assess the role of the TMPRSS2:ERG fusion transcript in the formation of bone metastases." (PMID 33634124, 2021). "More recently, combined detection of urinary prostate cancer gene 3 (PCA3) and TMPRSS2:ERG has been shown to improve the sensitivity for prostate cancer diagnosis." (PMID 33634124, 2021). "Bromhexine hydrochloride (BRH) is a TMPRSS2 inhibitor that can attenuate metastasis in prostate cancer mice models." (PMID 34527703, 2021). "The patient with advanced castration-resistant prostate cancer with neuroendocrine differentiation was a 53-year-old man with a tumour harbouring duplication of exons 1–3 in ATR, as well as BRCA2 and TMPRSS2-ERG somatic tumour mutations." (PMID 34040174, 2021). "TMPRSS2 is widely expressed in the lungs, nasal epithelium and gastrointestinal tract, and its regulation by androgens has been shown in the context of prostate cancer." (PMID 34835015, 2021). "TMPRSS2-ERG is the most common gene rearrangement in prostate cancer and is present in approximately 50% of prostate cancer tissues in Western countries." (PMID 34630112, 2021). "Currently, seven molecular subtypes of prostate cancer (PCa) are known, the most common of which being the subtype characterized by the presence of the TMPRSS2–ERG fusion transcript." (PMID 34205581, 2021). "The expression of PCAT5 was confirmed in the VCaP prostate cancer cell line harboring the TMPRSS2:ERG fusion and was significantly decreased as a result of siRNA-mediated knock-down of ERG." (PMID 33634124, 2021). "Meanwhile, the TMPRSS2: ERG fusion gene has been associated with prostate cancer and serves as a biomarker for the diagnosis and stratification of androgen-sensitive prostate cancer." (PMID 34063247, 2021). "Collectively, the functions and mechanisms of TMPRSS2-ERG increase the opportunities for finding new therapeutic targets for prostate cancer." (PMID 34630112, 2021). "RUNX1 knockdown decreased the expression of TMPRSS2 in the human prostate cancer cell line, whereas increased the expression of CTSB/L genes." (PMID 34407143, 2021). "Several other TMPRSS2:ERG fusion events with different junction sites have also been described to occur in prostate cancer clinical samples with lower frequency." (PMID 33634124, 2021). "Other common mechanisms of oncogenesis involve fusions which promote aberrant transcription, such as TMPRSS2-ERG seen across many prostate cancers." (PMID 34573358, 2021). "For example, TMPRSS2‐ERG fusions are observed in 40% of prostate cancers, and p1/q19 chromosomal co‐deletions are observed in 30% of lower‐grade gliomas." (PMID 33769711, 2021). "The human transmembrane protease serine 2 (TMPRSS2) protein plays an important role in prostate cancer progression." (PMID 34692848, 2021).
prostate carcinoma (continued). "By these reasons, it is important to predict the cancer patients’ susceptibility to SARS‐CoV‐2 infection and the disease outcome via assessing TMPRSS2 expression in cancer tissues, particular in prostate cancer tissues and related bioinformatics analyses." (PMID 33609069, 2021). "Most studies have been carried out on prostate cancers, which contain the transmembrane protease, serine 2, gene-erythroblast transformation-specific-related gene (TMPRSS2-ERG) gene fusion." (PMID 36046118, 2021). "The most common genetic alteration in prostate cancer consists of a chromosomal rearrangement between the androgen-regulated gene TMPRSS2 and the ETS transcription factor ERG." (PMID 34638309, 2021). "Biomolecular modeling, surface plasmon resonance, and biochemical analysis established α1AT as inhibitor of TMPRSS2, a cell surface serine protease that is involved in cell-cell and cell-matrix interactions, and in prostate cancer metastasis." (PMID 33741941, 2021). "TMPRSS2 is an androgen-regulated serine protease involved in human prostate cancer progression and metastasis." (PMID 34341347, 2021). "Although earlier studies primarily focused on prostate cancer, more recent studies have investigated TMPRSS2/ACE2 integrity as related to SARS-CoV-2 infection." (PMID 34063247, 2021). "Assessments of TMPRSS2 rearrangements by fluorescence in situ hybridization (FISH) in separated foci of prostate cancers revealed interfocal heterogeneity and intrafocal homogeneity, indicating that individual foci are the result of clonal expansion." (PMID 33634124, 2021). "In prostate cancer, a key event is the oncogenic activation of transmembrane protease serine 2 (TMPRSS2), via AR signaling." (PMID 34341347, 2021). "Enzalutamide, an approved drug for prostate cancer, acts on TMPRSS2 expression, a key mediator for SARS-CoV-2 infection." (PMID 33558541, 2021). "The included VCaP cell line is commonly used as a model system for prostate cancer and is known to contain the TMPRSS2-ERG fusion." (PMID 34891161, 2021). "Tomlins used FISH to evaluate the TMPRSS2:ETV1 fusion gene in paraffin sections of prostate cancer and found that, fusion signals were observed in an average of 31% of the 100 cancer cells in the positive case (Supporting Online Material page 3)." (PMID 34676167, 2021). "Multiple studies have shown that TMPRSS2 is an androgen receptor (AR) target gene in prostate cancer cells." (PMID 34210968, 2021). "On the other hand, EV-related biomarkers have been described as highly tumor-specific, reflecting the peculiarities of their tissues of origin; EVs enriched in TMPRSS2:ERG fusion transcript in prostate cancer are an example." (PMID 34445131, 2021). "For instance, fusions of ETS transcription factor gene ERG with promoter elements of TMPRSS2 are observed in roughly 50% of prostate cancers, as well as MTOR-TP53BP1, SLC45A2-AMACR, and MAN2A1-FER fusions found at lower frequencies." (PMID 34573358, 2021). "We first surveyed TMPRSS2 and AR expression across a panel of well-characterized prostate cancer cell lines and two previously established organoid lines MSKPCa1 and MSKPCa321." (PMID 33558541, 2021). "An example is TMPRSS2–ERG, generated in prostate cancer via an intron deletion between TMPRSS2 and ERG on chromosome 21q22.2-3." (PMID 33557176, 2021). "TMPRSS2-ERG is a highly prevalent fusion gene in prostate cancer (∼50% of the diagnosed patients), resulting in TMPRSS2-driven up-regulation of ERG." (PMID 34891161, 2021). "Chromatin immune-precipitation and parallel sequencing showed that TMPRSS2–ERG was involved in the development of prostate cancer through disruption of lineage-specific differentiation and potentiation of the EZH2-mediated de-differentiation program." (PMID 34399734, 2021). "They showed that the TMPRSS2:ERG positive VCaP prostate cancer cells overexpressed the fusion product when treated with synthetic androgens." (PMID 33634124, 2021).
prostate carcinoma (continued). "As the TMPRSS2-ERG fusion is the most common alteration in prostate cancer, molecular targeting of it has gained attraction as a potential therapeutic strategy." (PMID 33634124, 2021). "Enzalutamide, an AR inhibitor approved for use in CRPC patients, can reduce TMPRSS2 expression in prostate cancer cells." (PMID 33558541, 2021). "Next to TMPRSS2:ERG fusions, genomic deletions at various chromosomal loci represent the most prevalent recurrent genetic alterations in prostate cancer where specific mutations of cancer genes are rare." (PMID 32377272, 2020). "In the fusion transcript TMPRSS2-ETV4, found in prostate cancer patients, a sequence upstream of the TMPRSS2 gene is juxtaposed to the last 9 bp of intron 2 of ETV4 gene." (PMID 32791988, 2020). "The combination of rucaparib with radiation therapy was synergistic for prostate cancer cells expressing the TMPRSS2:ERG gene fusion, as these cells showed enhanced sensitivity towards rucaparib, which increased radiation response." (PMID 33233320, 2020). "Well-known prostate cancer-associated genes such as PCA3, TMPRSS2, and CST3 were found to be upregulated in urinary sediment RNA from the higher-risk cancer group compared to those lower-risk group." (PMID 33363151, 2020). "In PCa, TMPRSS2-ERG is found at high frequency in prostate cancer and it’s over-expressed near to 50% of tumors." (PMID 32694934, 2020). "Similar in vitro antiviral effects on SARS-CoV and MERS-CoV have also been described with protease inhibitors targeting the transmembrane serine protease 2 (TMPRSS2), an androgen-regulated gene commonly known in prostate cancer biology." (PMID 32824674, 2020). "TMPRSS2 displayed a higher expression level in bladder cancer, kidney cancer, liver cancer, and prostate cancer, and a lower expression level was found in most other cancers." (PMID 33193689, 2020). "TMPRSS2:ERG fusions affect about 50% of prostate cancers and lead to a constitutive overexpression of the transcription factor ERG." (PMID 32143573, 2020). "In prostate cells, TMPRSS2 is a constituent of the normal seminal fluid and present in the secretory epithelium; moreover, its expression is controlled by androgens in prostate cancer cells and tissues." (PMID 32764454, 2020). "Comparing RWPE-1 data with those of the TMPRSS2-ERG fusion-positive VCaP prostate cancer cells provides even information about those genes which have become under the control of the mis-expressed ERG in the cancer cells." (PMID 31818883, 2020). "The TMPRSS2:ERG fusion status of the prostate cancers on the TMA has been determined previously by FISH and IHC." (PMID 33339518, 2020). "About 50% of all prostate cancers carry a gene fusion linking the androgen‐regulated serine protease TMPRSS2 with the ETS‐transcription factor ERG resulting in an androgen‐related overexpression of ERG." (PMID 31736271, 2020). "Due to the heterogeneity of prostate cancer, the prevalence of the TMPRSS2-ERG fusion transcript varies by race." (PMID 32099679, 2020). "For example, AR, EGFR, DDR2 and MAP2K2 were connected with mtDNA genes in prostate cancer, and TMPRSS2, NF1, PIK3CA, BRCA1 and TOP1 were the top neighbors of mtDNA genes in multiple cancer types." (PMID 32024997, 2020). "In prostate cancer, a protease domain of around 32-kDa has been identified, indicating TMPRSS2 to be partly activated." (PMID 32764454, 2020). "ERG can fuse with TMPRSS2 promoter to form an oncogenic fusion gene that is commonly found in human prostate cancer, especially in hormone-refractory prostate cancer." (PMID 33575208, 2020). "For example, anti-androgen therapy commonly used in prostate cancer has the potential for use to block the entry of COVID19 to target cells through attenuation of TMPRSS2 expression." (PMID 33076397, 2020).
prostate carcinoma (continued). "Here, we included data on the TMPRSS2:ERG fusion (occurring in about 50% of prostate cancers), the most common recurrent chromosomal deletions (3p, 5q, 6q, 8p, 10q/PTEN, 12p, 12q, 13q, 16q, 17p, 18q), and the Ki67LI as well as AR protein expression levels." (PMID 32417965, 2020). "The biobank captured the most common genetic aberrations in prostate cancer, including TMPRSS2–ERG fusion, homozygous deletions of PTEN and CHD1, as well as typical copy number variations." (PMID 33135109, 2020). "Of note, TMPRSS2 RNA expression was highest in prostate cancer tissues, whereas renal tumors were featured among the lowest expressing tissues." (PMID 33330620, 2020). "The related kallikrein gene KLK2 had expression that was highly correlated with KLK3, as did TMPRSS2, one of the genes involved in the TMPRSS2:ERG translocation that is common in prostate cancer." (PMID 33303959, 2020). "The results showed that the expression of TMPRSS2 in prostate cancer tissues was significantly higher than that in normal tissues (value of p < 0.001) GES6956 further proves the higher result in prostate cancer compared with normal tissue." (PMID 33193689, 2020). "TMPRSS2:ERG fusions occur in almost half of all prostate cancers and induce overexpression of the transcription factor ERG." (PMID 33195694, 2020). "We describe the case of a patient who developed lung and prostate cancers, both harboring the TMPRSS2:ERG fusion." (PMID 33419298, 2020). "Overexpression of the TMPRSS2 gene under the action of androgens in prostate cancer cells and reduced expression of the TMPRSS2 gene in androgen-independent prostate cancer were detected." (PMID 32987757, 2020). "One of the most frequent promoter substitution (PS) events in cancer involve transcriptional activation of ERG through fusion with TMPRSS2, which occurs in approximately 40% of prostate cancers as a result of a genomic deletion on chromosome 17q2217." (PMID 33097743, 2020). "On a genetic level, about 50% of prostate cancer is characterized by gene fusion of the androgen responsive TMPRSS2 serin protease and the ETS-family transcription factor ERG." (PMID 33195694, 2020). "The second protein, necessary for SARS-CoV2 invasion into cells, the cell-surface serine protease TMPRSS2 is predominantly expressed in prostate epithelium, in high-grade prostate cancers, and in the majority of human prostate cancer metastases." (PMID 32450906, 2020). "TMPRSS2 protein is widely studied and known for its role in prostate cancer development; indeed, the transcription of the TMPRSS2 gene is regulated by androgenic hormones and a deregulation of androgen signaling determines prostate cancer progression." (PMID 32998451, 2020). "Prostate cancer patients usually carry the TMPRSS2/ERG (T/E) fusion gene, and T/E can activate the NF-κB pathway through phosphorylation of NF-κB p65 Ser536 (p536) to promote the occurrence and development of prostate cancer." (PMID 33061854, 2020). "The TMPRSS2 gene has been found to form fusions with transcription factors, the TMPRSS2-ERG gene fusion is present in ~50% of prostate cancer cases." (PMID 33076397, 2020). "Chromosomal deletions represent the second most frequent type of recurrent genomic aberrations in prostate cancer after TMPRSS2:ERG fusions." (PMID 32417965, 2020). "The most frequent gene fusion in prostate cancer is the TMPRSS2–ERG gene fusion, which comprise around 50% of prostate cancers." (PMID 32764454, 2020). "Oncogenic androgen-regulated TMPRSS2-ETS gene fusions are also found in upward of 50% of prostate cancers." (PMID 33310900, 2020). "About 50% of prostate cancers contain gene fusions connecting the androgen-regulated TMPRSS2 gene with the transcription factor ERG." (PMID 32377272, 2020). "The role of TMPRSS2 gene in prostate cancer is well-known; however, there are very few reports about the association of TMPRSS2 polymorphism with respiratory distress." (PMID 33101356, 2020).
prostate carcinoma (continued). "GOLM1, CD24, PSCA, and the gene fusion TMPRSS2-ERG were selected as overexpressed mRNAs in prostate cancer, whereas ANXA3 and SLC45A3 were selected as underexpressed mRNAs in prostate cancer for evaluation." (PMID 33172003, 2020). "About 50% of prostate cancers contain a gene fusion involving the androgen-regulated TMPRSS2 and the transcription factor ERG36,37." (PMID 32488048, 2020). "TMPRSS2–ERG fusions are being pursued as genomic biomarkers to predict treatment responses in prostate cancer (PCa)." (PMID 32992681, 2020). "Gene fusions involving TMPRSS2 are the most frequently reported across all malignancies, with approximately half of all prostate cancers containing TMPRSS2-ERG fusions." (PMID 32383760, 2020). "To test if the lead compounds alter protein stability or transactivation function, we used the VCaP prostate cancer cell line which harbors the TMPRSS2/ERG rearrangement." (PMID 32915889, 2020). "TMPRSS2:ERG fusions are observed in about 50% of prostate cancer resulting in permanent overexpression of the transcription factor ERG." (PMID 32677026, 2020). "This gene is also the most frequently altered in primary prostate cancers, and TMPRSS2 expression is strongly upregulated in response to androgens in prostate cancer cells and in human lung epithelial cell lines." (PMID 32824674, 2020). "Evidence from AR-negative prostate cancer cells shows that DNMT1 is associated with hypermethylation of TMPRSS2 gene and low expression level of TMPRSS2." (PMID 33243086, 2020). "Conversely, AR upregulates pathways in prostate cancer that increase genomic instability, such as the TMPRSS2-ERG gene fusion, which is present in a significant part of advanced prostate cancers." (PMID 32123273, 2020). "TMPRSS2-ERG has long been studied by the prostate cancer field as an oncogenic gene fusion under the control of the androgen-regulated TMPRSS2 promoter expressed in the majority of prostate cancers." (PMID 33310900, 2020). "The gene TMPRSS2 is closely relevant to prostate cancer as well, regulating many biological processes." (PMID 33193689, 2020). "As a prostate-specific gene, TMPRSS2 fuses with the transcription factor ERG gene in a large proportion of human prostate cancers and plays an important role in selected pathological processes." (PMID 33193689, 2020). "Mouse prostate organoids were modified to carry the TMPRSS2-ERG fusion, a genetic alteration present in more than 50% of prostate cancers that leads to high ERG expression driven from the androgen-responsive promoter of the TMPRSS2 gene." (PMID 32019175, 2020). "On the other hand, drugs that are able to inhibit a wide panel of human serine proteases, including TMPRSS2, are currently approved to treat prostate cancers and several inflammatory pathologies." (PMID 32784899, 2020). "CTCF staining was strongly linked to TMPRSS2:ERG rearrangement and ERG positivity in our set of prostate cancers (P < 0.0001)." (PMID 31736271, 2020). "Recurrent gene fusions were primarily identified in prostate cancer (TMPRSS2::ERG) and adenoid cystic carcinoma (MYB::NFIB) in 1.74% (9/517) and 1.35% (7/517), respectively in the overall cohort." (PMID 31491926, 2019). "FAT1 is a tumor suppressor gene that affects the WNT signaling pathway and TMPRSS2 is an AR-regulated gene that is involved in a gene fusion (TMPRSS2-ERG) in prostate cancer." (PMID 31434336, 2019). "More than half of all prostate cancers, particularly those of young patients, harbor fusions connecting the androgen-regulated TMPRSS2 gene with the transcription factor ERG." (PMID 31557128, 2019). "The aberrant activation of the ERG oncogenic pathway due to the TMPRSS2-ERG gene fusion is the major event that contributes to prostate cancer (PCa) development." (PMID 30718921, 2019). "The presence of prostate cancer-specific TMPRSS2-ERG fusion in both adenocarcinoma and small cell carcinoma of the same tumor cases suggests a direct lineage." (PMID 31146720, 2019).